IGF1R (insulin like growth factor 1 receptor)
Diseases named in the same sentence as IGF1R in open-access papers (continued):
Sharing a sentence is not in itself a finding about the gene and the disease.
colon carcinoma (125 papers, 2006 to 2025). "IGF1-R is often elevated in many cancer tissues including colon cancer and its activation has been linked to increased NF-κB activation and thus proliferation, survival, metastatic potential, and angiogenesis." (PMID 33477997, 2021). "Epidemiological studies have shown that the IGF-1R signaling pathway disruption is strongly associated with the development of several common cancers, including prostate, breast, and colon cancer." (PMID 34359752, 2021). "Recently, we demonstrated that IGF-1R kinase inhibitor PQIP causes marked antitumor activity in these colon cancer cell lines by abrogating the IGF-1R mediated activation of IRS1/Akt to inhibit survival signaling, and inducing apoptosis." (PMID 24173770, 2014). "Indeed, inhibition of the activation of the IGF/IGF-1R axis resulted in suppression of colonic premalignant lesions in an obesity-associated colon cancer model, which was also associated with hyperlipidemia, hyperinsulinemia, and hyperleptinemia." (PMID 22174655, 2011). "The functional significance of miR-497 in regulating malignant behaviour of colon cancer cells is echoed by its downregulation in colon cancer tissues in vivo, and is further supported by the negative association between its expression levels and the levels of IGF1-R." (PMID 22710713, 2013). "Other studies showed that miR-497 over-expression makes colon cancer cells more sensitive to apoptosis, partly due to IGF-1R downregulation." (PMID 41153350, 2025). "Western blotting analysis for the detection of IGF-1R protein levels in colon cancer tissue also led to congruent results." (PMID 41153350, 2025). "Remarkably, enhanced Klotho expression curtailed both tumor growth and invasion by impeding the IGF1R-mediated PI3K/Akt pathway in colon cancer cells." (PMID 40004457, 2025). "It was reported that CS notably inhibited proliferation and induced apoptosis of colon cancer cells through regulating the ERβ/MiR-95, IGF-1R and PI3K-Akt signaling pathways." (PMID 36755950, 2023). "The overexpression of IGF1R has been observed in a variety of cancers, including breast, lung, prostate, and colon cancer, making it an attractive target for cancer therapy." (PMID 37744271, 2023). "Overexpression of IGF1R, Bcl-xL and mTOR inhibits apoptosis and contributes to colon cancer cell survival and invasion." (PMID 36013453, 2022). "The primary strategy in treating colon cancer includes the arrest of IGF1R overexpression by small inhibitors, antibodies or the inhibition of its ligands." (PMID 36013453, 2022). "In colon cancer cells, TGFβ and IGF1R signaling activates PKA through regulation of ezrin phosphorylation." (PMID 33046439, 2021). "Chemo-resistant colon cancer cell lines had higher concentrations of nuclear IGF1R, and IGF1R translocation was enhanced by IGF1R blocking antibody ganitumab." (PMID 33918477, 2021). "MiR-133a is also able to inhibit cellular proliferation and colony formation by targeting SP1 protein that binds to IGF1-R promoter blocking IGF-1 involved in colon cancer progression." (PMID 34575979, 2021). "APC, SMAD4, NF1 (neurofibromin 1), ARID5B, NCOR1 (nuclear receptor corepressor 1), IGFR1R (insulin like growth factor 1 receptor) and GNAS (GNAS complex locus) were the most often mutated genes in patient-derived colon cancer cells." (PMID 33050525, 2020). "Despite relatively small patient numbers compared to common cancers, such as breast, lung, or colon cancer, our analysis represents the largest single-institutional experience of ES patients treated with IGF-1R mAbs." (PMID 32630797, 2020). "These in vitro and in vivo findings suggest that inhibition of MEK1/2 suppresses IGF-1R-inhibition-induced p70S6K1 activation in colon tumor cells, providing a new strategy for colon cancer therapy." (PMID 32843616, 2020).
colon carcinoma (continued). "Here, we discovered that prolonged treatment of colon cancer cells with IGF-1R inhibitors (BMS-754807 and GSK1838705A) stimulates p70 KDa ribosomal protein S6 kinase 1 (p70S6K1) activation, a well-known kinase signaling for cell survival." (PMID 32843616, 2020). "In this study, we found that extensive treatment of IGF-1R inhibitor induced phosphorylation of p70S6K1 in colon tumor cells." (PMID 32843616, 2020). "New evidence has demonstrated that the overexpressions of IGF-1 and IGF-1R contribute to the development and progression of colon cancer in patients and in an AOM-DSS-induced colorectal carcinogenesis model." (PMID 31480481, 2019). "It has been shown that IGF-1R signaling is important for proliferation of colon cancer cells and that IRS-1 is one of the main adaptor proteins required for IGF-1R signaling." (PMID 28414818, 2017). "An oncogenic pathway that is activated in 30% of human colon cancer is the type I Insulin Like Growth Factor Receptor (IGF-1R) signaling pathway." (PMID 28414818, 2017). "The high frequency of expression in colon cancer and membrane subcellular location make IGF-1R a potential target for fluorescent antibodies to enable cancer visualization, diagnosis, and FGS." (PMID 26731105, 2016). "The present study thus demonstrates that fluorophore-conjugated IGF-1R antibodies selectively visualize metastatic colon cancer and have clinical potential for improved diagnosis and fluorescence-guided surgery." (PMID 26731105, 2016). "In vitro imaging confirmed that the conjugated antibody bound to IGF-1R on the outer membrane of colon cancer cells." (PMID 26731105, 2016). "The present report demonstrates the feasibility of IGF-1R targeted fluorophore-conjugated antibodies to visualize metastatic colon cancer in appropriate mouse models." (PMID 26731105, 2016). "Labeling with fluorophore-conjugated IGF-1R antibody demonstrated fluorescent foci on the membrane of colon cancer cells." (PMID 26731105, 2016). "We also had previously investigated that simvastatin induces the apoptosis of colon cancer cells through control of the expression of IGF-1R and IGF-1R signaling pathways." (PMID 26966430, 2016). "In conclusion, we have shown that fluorophore-conjugated IGF-1R antibody is very effective in labeling colon cancer in mouse models." (PMID 26731105, 2016). "Formal bio-distribution analysis and further studies with colon cancer PDOX models are needed to confirm that IGF-1R targeted imaging can be used in clinical settings." (PMID 26731105, 2016). "Subcutaneous, orthotopic, and liver metastasis models of colon cancer in nude mice were targeted with the fluorescent IGF-1R antibodies." (PMID 26731105, 2016). "Using IGF-1R also has additional clinical potential since the overexpression of IGF-1R correlates with shorter median survival of colon cancer patients who undergo surgery and adjuvant chemotherapy." (PMID 26731105, 2016). "It has reported that overexpression of Klotho inhibits growth and invasion through inhibition of IGF1R-mediated PI3K/AKT pathway in colon cancer cells." (PMID 26499380, 2015). "This potential link was further supported by work from Lahm and colleagues that described frequent IGF-1R overexpression in human colon cancer cells." (PMID 26528439, 2015). "In this work, we present evidences to indicate targeting of IGF1R by let-7d-5p in the regulation of IGF1R in colon cancer cells." (PMID 25287248, 2014). "We performed MTT assays to study the effect of MK-2206 on proliferation of IGF1R-dependent colon cancer cells." (PMID 24581231, 2014). "Our collective data confirmed that let-7d-5p targeted IGF1R at one of the three predicted sites to result in down-regulated IGF1R expression in colon cancer cells." (PMID 25287248, 2014). "The current study aimed to investigate the role of phloroglucinol on apoptosis and IGF-1R signaling pathways in HT-29 colon cancer cells as a potential therapeutic target in cancer therapy." (PMID 24970012, 2014).
colon carcinoma (continued). "IGF-1R protein and mRNA expression decreased significantly after 24 h of phloroglucinol treatment in HT-29 colon cancer cells." (PMID 24970012, 2014). "Stable knockdown of Akt2 in the IGF1R-dependent and highly metastatic colon cancer cell line GEO was performed to give a better understanding of the mechanism of cell death mediated by loss of pEzrin." (PMID 24581231, 2014). "In conclusion, we have demonstrated that phloroglucinol induced apoptosis via an apoptotic pathway involving growth factors, accounting for the effect of phloroglucinol on IGF-1R regulated signaling pathways in HT-29 colon cancer cells." (PMID 24970012, 2014). "In this study, we investigated the anticancer effects of phloroglucinol on insulin-like growth factor-1 receptor (IGF-1R) signaling in HT-29 human colon cancer cells." (PMID 24970012, 2014). "IGF1R is abundantly expressed in normal colorectal cells and in early-stage colon cancers but the expression is down-regulated in advanced-stage invasive colorectal cancers." (PMID 25287248, 2014). "Similar results were confirmed in 2 additional IGF1R-dependent colon carcinoma cell lines GEO and CBS." (PMID 24083380, 2013). "In this study, we utilized the IGF1R-dependent GEO human CRC cell line that was isolated from a CRC patient's primary colonic carcinoma." (PMID 27340651, 2013). "Although early phase clinical trials demonstrated that (IGF1R) specific antibodies are increasing sensitivity of colon cancer stem cells to chemotherapy, phase III results were unsatisfactory." (PMID 23476808, 2013). "A crosstalk between IGF-1R and the Wnt pathway has been reported in colon cancer, oligodendroglial cells, and chondrocytes." (PMID 23663564, 2013). "While its expression is commonly reduced in colon cancer cells in vitro and in vivo relative to normal colon epithelial tissues, introduction of exogenous miR-497 into colon cancer cells resulted in downregulation of IGF1-R and decreased activation of Akt." (PMID 22710713, 2013). "Previous work from our laboratory have extensively used Transferrin and Insulin (jointly termed here as GF or growth factors) in combination to activate IGF-1R-mediated cell survival signaling in colon cancer cells." (PMID 24083380, 2013). "Based on these findings, the effect of the IGF-1R-inhibitory cyclolignan picropodophyllin (PPP) was assessed in the four colon carcinoma cell lines HT-29, HCT-116, DLD-1 and CaCO-2." (PMID 22159423, 2012). "The treatment of colon cancer cell lines with the IGF-1R inhibitor PPP strongly impaired proliferation and survival, and also negatively affected cell attachment and migration." (PMID 22159423, 2012). "Recently, mir-493 (curiously also located on chromosome 14q32) was shown to be capable of inhibiting liver metastasis in a colon cancer model by targeting IGF1R." (PMID 22747855, 2012). "High IGF-1 levels have been found in several sarcoma subtypes and IGF-1R overexpression in breast, lung, prostate, or colon cancer has been shown to accelerate cancer progression and enable anchorage-independent growth." (PMID 24212944, 2011). "Expression of IGF-1R by immunohistochemistry has been found in more than half of colon cancer specimens or cell lines, and its affect upon colon cancer oncogenesis and progression has been observed in a number of preclinical models." (PMID 24212944, 2011). "In this study, resveratrol at 100-150 μM suppressed IGF-1R/Akt and Wnt/β-catenin signaling pathway proteins in the HT-29 colon cancer cell lines." (PMID 20504360, 2010). "The effect of resveratrol on IGF-1R is similar to the inhibitory effects of IGF-1R siRNA on the proliferation of colon cancer cells via suppressing IGF-1R and the downstream kinases, and the Wnt/β-catenin signaling pathway." (PMID 20504360, 2010).
colon carcinoma (continued). "IGF-1R siRNA suppressed colon cancer cell proliferation, and the cell numbers were lower than the siRNA control group." (PMID 20504360, 2010). "In conclusion, we have shown resveratrol to suppress IGF-1 (IGF-1 levels are elevated during obesity) induced cell proliferation and elevate apoptosis in human colon cancer cells, and elucidated the mechanisms of action using IGF-1R siRNA." (PMID 20504360, 2010). "For instance, high levels of IGF-1R in patients with colon cancer, as compared to healthy control, could indicate poor prognosis." (PMID 36233084, 2022). "Paracrine and autocrine mechanisms of IGF-II action in colon cancer were documented, as cancer-associated fibroblasts in tumor stroma were identified as a source of up-regulated IGF-II which, in turn, activates pro-survival IGF1R/IR signaling." (PMID 36013453, 2022). "Similar results were also obtained in colon cancer cell lines: IGF1 binding to IGF1R disrupts the E-cadherin/IGF1R interaction on cell surface with subsequent repositioning of the IGF1R and E-cadherin from cell-to-cell to focal contacts, thereby leading to enhanced cell migration." (PMID 33673232, 2021). "For instance, it targeted IGF1R to suppress the proliferation and invasion of colon cancer cells." (PMID 34604211, 2021). "PDCD4 could overcome the resistance to an IGF-1R/IR Inhibitor in colon carcinoma cells, which could be used for the treatment of colon cancer." (PMID 32962686, 2020). "APC, SMAD4 (SMAD family member 4), NF1 (neurofibromin 1), ARID5B, NCOR1 (nuclear receptor co-repressor 1), IGFR1R (insulin like growth factor 1 receptor) and GNAS (GNAS complex locus) were the most often mutated genes in patient-derived colon cancer cells, YUMC-C1 and YUMC-C2." (PMID 33050525, 2020). "Thus, phosphorylation of MEK1/2 is critical for p70S6K1 activation in colon cancer cells when IGF-1R is inhibited." (PMID 32843616, 2020). "Dallas and colleagues used an oxaliplatin-resistant colon cancer model and showed that the suppression of cancer cell development and progression could be achieved by IGF-1R inhibition." (PMID 30987250, 2019). "Importantly, IGF1R phosphorylation was reduced in colon tumors from p38α‐ΔMC mice compared to WT mice." (PMID 29907597, 2018). "Using the same hypothesis-driven supervised approach focused on IGF pathway member expression, Pavlicek and al., also identified IGFBP5 as a biomarker of colon cancer cells sensitivity to another IGF1R tyrosine kinase inhibitor, Figitumumab." (PMID 28882129, 2017). "EGCG also inhibits IGF1R phosphorylation in human colon cancer SW837 cells." (PMID 27941682, 2016). "The goal of the present manuscript was to demonstrate that a fluorescent antibody to IGF-1R could identify the extent of liver metastasis in orthotopic models of colon cancer better than standard bright light visualization, and we achieved this goal." (PMID 26731105, 2016). "A previous report on colon cancer showed that attenuated IGF-1R protein levels could suppress cell proliferation and elevate apoptosis even in the presence of IGF-1 via suppression of IGF-1R/Akt/Wnt signaling pathways and activation of p5332." (PMID 27646050, 2016). "The goal of the present study was to determine whether insulin-like growth factor-1 receptor (IGF-1R) antibodies, conjugated with bright fluorophores, could enable visualization of metastatic colon cancer in orthotopic nude mouse models." (PMID 26731105, 2016). "IGF-1R is expressed in 51~100% of the colon cancers depending on the study." (PMID 26731105, 2016). "Previous studies have identified that IGF1R is also a specific target of miR-145 in colon cancer cells, miR-122 in liver cancers, miR-7 in tongue squamous cell carcinoma cells, miR-375 in esophageal squamous cell carcinoma, and let-7c in regulation of glucose metabolism." (PMID 24410957, 2014). "IGF1R-dependent colon cancer cells (GEO and CBS) were used for the study." (PMID 24581231, 2014).
colon carcinoma (continued). "Interestingly, it was previously shown that miR-145 can target insulin receptor substrate-1 (IRS-1) and IGF1R in colon cancer cells." (PMID 25474488, 2014). "IGF-1R is an attractive drug target for the treatment of colon cancer." (PMID 24182354, 2013). "Regardless of the high levels of miR-424, colon cancers with low miR-497 expression displayed relatively high levels of IGF1-R, whereas high miR-497 expression was associated with relatively low levels of IGF1-R." (PMID 22710713, 2013). "Similarly, normal colon cancer mucosa that had in general higher levels of miR-497 than colon cancer tissues expressed relatively low levels of IGF1-R." (PMID 22710713, 2013). "IGF-1 binding to IGF-1R stimulates downstream proliferating pathways such as the PI3K/Akt and Ras signaling resulting in increased human colon cancer cell proliferation, thus suppressing IGF-1R might attenuate proliferation." (PMID 20504360, 2010). "Furthermore, it was speculated that IGF-1R plays a role in the resistance of colon cancer cells to drugs and especially to oxaliplatin." (PMID 41153350, 2025). "Recent studies based on TCGA analysis revealed that, in human colon cancer specimens, a stronger activity of β-catenin/TCF responsive promoter was associated with a higher transcription of IGF2 and IGF1R, which can be important in design of therapies employing IGF1R/IR inhibitors." (PMID 31623387, 2019). "Indeed, beneficial effects of combining IGF-1R inhibitors with paclitaxel have been reported in non-small cell lung cancers, with topotecan in Wilms tumor cells, and with irinotecan in colon cancers." (PMID 26274927, 2015). "In human colon cancers, expression of Klotho was downregulated and correlated with tumor invasion and Dukes staging, while overexpression of Klotho inhibited cell proliferation and invasion through inhibition of IGF1R-mediated PI3K/AKT pathway in colon cancer cells." (PMID 26499380, 2015). "Because the PI3K/Akt pathway also has an important role in regulating migration and invasion of malignant cells, we investigated whether the regulatory effect of miR-497 on IGF1-R/PI3K/Akt signalling is also reflected in its impact on colon cancer cell invasive behaviour." (PMID 22710713, 2013). "In liver cancer, IGFBP7 induces anti-tumor effects by binding to the IGF1 receptor (IGF1R) to inhibit IGF signaling; in colon cancer, IGFBP7 down-regulates EMT to promote liver metastasis." (PMID 37568781, 2023). "Simvastatin prompts the apoptosis of human colon cancer cells and inhibits IGF-1-induced ERK and Akt expression via the downregulation of IGF-1R expression and pro-apoptotic ERK activity." (PMID 37760764, 2023). "Curcumin enhances the cytotoxic effects of 5-FU and oxaliplatin in colon cancer cells through the downregulation of COX-2 and the modulation of EGFR and insulin-like growth factor 1 receptor (IGF-1R)." (PMID 37376060, 2023). "Similar results were also achieved when curcumin was used to treat FOLFOX-surviving colon cancer cells, highlighting the importance of EGFR/IGF-1R/Akt signaling inhibition by curcumin in chemo-resistant cells." (PMID 34867402, 2021). "Upregulation of the IGF1R pathway constitutes a common paradigm shared with other receptor tyrosine kinases such as EGFR, HER2, and MET in different cancer types, including colon cancer." (PMID 34065119, 2021). "In this study, we have uncovered a novel crosstalk between TGF-β and IGF-1R signaling pathways through the adaptor protein, IRS-1, in colon cancer cells." (PMID 28414818, 2017).